GPD1L (glycerol-3-phosphate dehydrogenase 1 like)
Description:
Plays a role in regulating cardiac sodium current; decreased enzymatic activity with resulting increased levels of glycerol 3-phosphate activating the DPD1L-dependent SCN5A phosphorylation pathway, may ultimately lead to decreased sodium current; cardiac sodium current may also be reduced due to alterations of NAD(H) balance induced by DPD1L.
Synonyms: GPD1-L; KIAA0089
Tractability: Small molecule: a structure with a bound ligand is known; it has a high-quality binding pocket. Antibody: its Gene Ontology location is reachable by antibodies, with high confidence. PROTAC: ubiquitination databases record sites on it; its protein half-life has been measured.
Gene: Protein-coding gene on chromosome 3 (32,105,689 to 32,168,715, forward strand). Ensembl gene ENSG00000152642.
Subcellular location: Cytoplasm
Pathways (Reactome):
Metabolism: Synthesis of PA
Gene Ontology:
Molecular function: glycerol-3-phosphate dehydrogenase (NAD+) activity; protein binding; sodium channel regulator activity; transmembrane transporter binding; glycerol-3-phosphate dehydrogenase [NAD(P)+] activity; NAD binding; oxidoreductase activity, acting on the CH-OH group of donors, NAD or NADP as acceptor; protein homodimerization activity
Biological process: NAD+ metabolic process; positive regulation of protein localization to cell surface; positive regulation of sodium ion transport; regulation of heart rate; regulation of ventricular cardiac muscle cell membrane depolarization; ventricular cardiac muscle cell action potential; carbohydrate metabolic process; glycerol-3-phosphate catabolic process; glycerol-3-phosphate metabolic process
Cellular component: extracellular exosome; plasma membrane; cytosol; cytoplasm; membrane
Genetic constraint (gnomAD): Loss-of-function variants: 14 observed, 22.71 expected, observed/expected ratio (o/e) 0.62, 90% interval 0.41 to 0.96. The upper end of that interval is the gene's LOEUF score, 0.96, which puts it in group 4 of 6, group 1 being the genes least tolerant of losing a copy. Missense variants: 259 observed, 328.87 expected, observed/expected ratio (o/e) 0.79, 90% interval 0.71 to 0.87. Synonymous variants: 142 observed, 124.39 expected, observed/expected ratio (o/e) 1.14, 90% interval 1 to 1.31.
Gene-disease validity (ClinGen):
ClinGen rates the evidence that GPD1L causes each of these diseases.
Brugada syndrome 1 (autosomal dominant): Disputed. Any Brugada syndrome in which the cause of the disease is a mutation in the SCN5A gene.
Homologues: Orthologues: chimpanzee GPD1L (100% identical), macaque GPD1L (99% identical), guinea pig GPD1L (97% identical), mouse Gpd1l (95% identical), rat Gpd1l (94% identical), pig GPD1L (93% identical), tropical clawed frog gpd1l (84% identical), zebrafish gpd1l (83% identical), dog GPD1L (77% identical), Drosophila melanogaster Gpdh1 (60% identical), Caenorhabditis elegans gpdh-2 (58% identical), Caenorhabditis elegans gpdh-1 (49% identical), and 2 more. Paralogues in human: GPD1 (71% identical).
Diseases named in the same sentence as GPD1L in open-access papers:
GPD1L is named in the same sentence as 47 diseases in open-access papers, as found by Europe PMC text mining. Sharing a sentence is not in itself a finding about the gene and the disease. The quoted sentences say what the papers report.
Brugada syndrome (15 papers, 2013 to 2026). A genetically heterogeneous condition characterized by complete or incomplete right bundle branch block accompanied by ST elevation in leads V1-V3. "Other genes, such as SCN1B, SCN2B, SCN3B, and GPD1L, contribute to reduced INa and Brugada syndrome, with various clinical phenotypes associated with these mutations." (PMID 39583597, 2024). "This phenomenon was believed to underlie the decreased channel trafficking as well as current amplitude of NaV1.5 seen in glycerol 3-phosphate dehydrogenase 1-like (GPD1L) mutations associated with the Brugada syndrome and sudden infant death syndrome." (PMID 35588786, 2022). "A GPD1L mutation causes Brugada syndrome and other inherited arrhythmia syndromes by affecting Na + channel trafficking to the plasma membrane." (PMID 36064558, 2022). "Additional functional studies are needed to clarify the role of GPD1L c.560A>G (p.Asn187Ser) variant in the pathogenesis of Brugada syndrome." (PMID 33829027, 2021). "GPD1-L catalyses the conversion of sn-glycerol 3-phosphate to glycerone phosphate and binds to the SCN5A ion channel protein; mutations in the GPD1L gene have been linked to Brugada syndrome and to sudden infant death syndrome." (PMID 24715918, 2014). "It demonstrates a possible link between dead-in-bed syndrome and Brugada syndrome, thereby supporting earlier work, albeit for a GPD1L gene variant of unclear clinical significance but with supportive in vitro evidence." (PMID 24715918, 2014). "Mutations in the GPD1L gene were first reported in 2007 to be causative of sudden infant death and familial Brugada syndrome." (PMID 24715918, 2014). "Previous studies have shown that GPD1L mutations can cause arrhythmias such as Brugada syndrome." (PMID 36064558, 2022). "Furthermore, the A280V mutation in glycerol-3-phosphate dehydrogenase 1-like (GPD1-L) protein, which causes Brugada syndrome, reduces INa via increasing cytosolic NADH and mitochondrial ROS levels." (PMID 33659284, 2021). "Previous literature data suggest that genetic alterations in the GPD1L gene are related to cardiac rhythm disorders; Brugada syndrome, sudden infant death syndrome (SIDS), and long QT syndrome." (PMID 33829027, 2021). "Patient 20 harbored a rare pathogenic/likely pathogenic variant (c.839C > T, p.Ala280Val; rs72552291) in the GPD1L gene that has been shown to decrease inward SCN5A Na + current and cause Brugada syndrome." (PMID 32695137, 2020). "GPD1L is a crucial interacting protein of SCN5A, a gene encoded sodium channel α‐subunit Nav1.5 and mainly associated with Brugada syndrome (BrS)." (PMID 29077258, 2018). "To date, mutations in the sodium channel, voltage-gated, type V, alpha subunit gene and glycerol-3-phosphate dehydrogenase 1-like gene are estimated to account for approximately 28% of Brugada syndrome probands." (PMID 23506330, 2013). "Mutations in the GPD1L (glycerol-3-phosphate dehydrogenase-1–like) gene and in the CACNA1C and CACNB2b (alpha and beta subunits of the L-type calcium channels) genes have been associated with Brugada syndrome." (PMID 41062843, 2026). "Beyond its established role in Brugada syndrome pathogenesis through SCN5A modulation, recent investigations reveal GPD1L’s capacity to destabilize the oxygen-sensitive transcriptional regulator HIF-1α via prolyl hydroxylase (PHD) activation." (PMID 40538846, 2025).
sudden infant death syndrome (7 papers, 2014 to 2024). Unexpected death in infancy which remains unexplained following autopsy, review of the medical history, and investigation of the death circumstances and death scene. "Additional studies suggested GPD1L-A280V decreases NaV1.5 membrane expression, and that GPD1L mutations were associated with sudden infant death syndrome (SIDS) on molecular autopsies." (PMID 38962240, 2023). "At present, only a few GPD1L variants have been identified in patients affected by BrS, sudden infant death syndrome, diabetic dead-in-bed syndrome, cardiac conduction disorder, atrial fibrillation and early repolarisation syndrome, but only 6 of them have been functionally characterized." (PMID 38036776, 2024). "In this regard, critical significance of G3P turnover is indicated by mutations in G3P dehydrogenase 1-like (GPD1-L) protein, which is highly expressed in the heart, that are linked to Brugada and sudden infant death syndromes characterized by vulnerability to metabolic stress." (PMID 26378442, 2015). "Mutations in four of these genes, i.e. GPD1L, MOG1, SNTA1, CAV3 have been linked with AF and long QT syndrome (LQTS), Brugada syndrome (BrS) or sudden infant death syndrome (SIDS)." (PMID 28837624, 2017).
Obesity (6 papers, 2017 to 2025). Accumulation of substantial excess body fat. "Future studies should explore isoform-specific effects, given GPD1L’s known splice variants in cardiovascular systems, and therapeutic potential in obesity-associated CRC models." (PMID 40538846, 2025). "Our study addresses this gap by identifying GPD1L, a gene recently implicated in obesity pathogenesis through genome-wide association studies, as a novel tumor suppressor in CRC, thereby providing mechanistic insights into obesity-driven oncogenesis." (PMID 40538846, 2025). "GPD1L has been shown to be an important causal candidate gene for obesity‐associated complications in a cohort of humans undergoing weight loss intervention in gene expression profiling in human abdominal SAT." (PMID 40229590, 2025). "In the meta-analysis, GPD1L was identified to be significantly associated with obesity by Fisher’s method, as well as by combining effect size method." (PMID 28496128, 2017). "Building upon these observations, we hypothesize that GPD1L dysregulation may mechanistically connect obesity-associated metabolic dysfunction with CRC progression." (PMID 40538846, 2025). "Furthermore, GPD1L was recently identified as potentially playing a causal role in obesity and insulin resistance." (PMID 35739539, 2022). "This novel approach resulted in the discovery of GPD1L as the most important candidate causal gene for obesity that may serve as an effective target for therapeutic intervention." (PMID 28496128, 2017). "Notably, overweight patients exhibited accentuated GPD1L downregulation, aligning with preclinical models demonstrating diet-induced obesity reduces hepatic GPD1L expression by 63% (P<0.001), suggesting a potential mechanism for obesity-associated CRC progression." (PMID 40538846, 2025). "For some of the most up‐ or downregulated DEGs, namely NQOI, GPD1L, and TNMD, the link to obesity, weight loss, or diabetes mellitus is described." (PMID 40229590, 2025). "This study establishes GPD1L downregulation as a molecular hallmark of CRC progression, mechanistically linking obesity-associated metabolic dysregulation to metastatic dissemination." (PMID 40538846, 2025). "Our findings provided strong support for the important role of GPD1L and also shed light on its molecular functional mechanisms in the etiology of obesity and insulin resistance." (PMID 28496128, 2017). "The present study linked the regulation of miR-210 on GPD1L, the biological importance of GPD1L in adipose tissue, obesity and insulin resistance with the hypoxia-induced feedback loop." (PMID 28496128, 2017). "More importantly, the most promising candidate causal gene GPD1L and its role in the etiology of HFD-induced obesity were highlighted." (PMID 28496128, 2017). "Taken together, these findings in various metabolic measures provided strong supporting evidence for an important role for GPD1L in obesity." (PMID 28496128, 2017). "The results indicated that increased GPD1L in adipose tissue may have a significant therapeutic potential in reducing obesity and insulin resistance." (PMID 28496128, 2017). "It indicated that increased GPD1L which can inhibit HIF-1α activity in adipose tissue might have significant therapeutic potential in reducing obesity and insulin resistance." (PMID 28496128, 2017). "Although the biological function of the gene GPD1L in human adipose tissue and obesity requires further investigation, our findings and other evidence supported that GPD1L in adipose tissue may play a pivotal role in the molecular mechanism of obesity." (PMID 28496128, 2017). "Our findings indicated that increased GPD1L which can inhibit HIF-1α activity in adipose tissue might have a significant therapeutic potential in reducing obesity and insulin resistance." (PMID 28496128, 2017).
Obesity (continued). "The genes glycerol‐3‐phosphate dehydrogenase 1 like (GPD1L), gasdermin B (GSDMB) and molybdenum cofactor synthesis 1 (MOCS1) were upregulated after LIWL, and expression was increased in SAT of individuals with or without obesity of the LATC and OA cohorts." (PMID 40229590, 2025).
Arrhythmia (3 papers, 2018 to 2022). Any cardiac rhythm other than the normal sinus rhythm. "We have employed whole‐exome sequencing (WES) in combination with arrhythmia‐related gene‐filtering to explore the possible causative gene for this family, a novel nonsense heterozygous mutation (c.565C>T/p.Arg189*) of GPD1L was identified may underlie the inherited arrhythmia." (PMID 29077258, 2018). "Most of these variants were located in genes associated with inherited arrhythmias and arrhythmic cardiomyopathies, such as MYBPC3, KCNQ1, TTN, CASQ2, GPD1L, DPP6, HCN4 and NEXN." (PMID 36008935, 2022). "The levels of GPD1L decreasing may disturb the function of Nav1.5 and induce arrhythmia and syncope in the end." (PMID 29077258, 2018).
colorectal cancer (3 papers, 2023 to 2025). A primary or metastatic malignant neoplasm that affects the colon or rectum. "Previous studies have found that glycerol‐3‐phosphate dehydrogenase 1‐like (GPD1L) is associated with the progression of tumours such as lung cancer, colorectal cancer and oropharyngeal cancer, but the potential mechanism in RCC is still unclear." (PMID 37382962, 2023). "Quantitative PCR analysis confirmed differential GPD1L expression across colorectal cancer cell (SW480, SW620, DLD-1, HCT116, LOVO) and normal colonic NCM460 cells." (PMID 40538846, 2025). "Studies have shown that GPD1L also plays an important role in the regulation of cardiac sodium current, colorectal cancer and oropharyngeal cancer." (PMID 37382962, 2023). "A few studies have identified the role of GPD1L in the progression of tumours, such as lung cancer, colorectal cancer and oropharyngeal cancer, but the potential mechanism in RCC is still unclear." (PMID 37382962, 2023).
Insulin resistance (3 papers, 2017 to 2025). Increased resistance towards insulin, that is, diminished effectiveness of insulin in reducing blood glucose levels. "Consistently, in the present study GPD1L was found to be significantly negatively correlated with the measure of insulin resistance, HOMA-IR." (PMID 28496128, 2017). "Especially, the highly significant negative correlation of GPD1L with WHR and FM provided evidence for a potential role in central obesity which was highly related to insulin resistance." (PMID 28496128, 2017).
coronary artery disease (2 papers, 2015 to 2016). "Variants in GPD1L are associated with risk of sudden death in patients with coronary artery disease." (PMID 25590576, 2015). "Notably, most previous studies revealed GPD1L was associated with increased risk of sudden cardiac death (SAD) in patients with coronary artery disease (CAD)." (PMID 28040802, 2016).
gastric cancer (2 papers, 2025). A primary or metastatic malignant neoplasm involving the stomach. "Multivariate Cox regression confirmed GPD1L as an independent prognostic indicator (HR=0.936, P=0.032), reinforcing findings from gastric cancer studies where GPD1L loss predicted aggressive phenotypes." (PMID 40538846, 2025). "In gastric cancer cells, the proteins glycerol-3-phosphate dehydrogenase 1 (GPD1) and glycerol-3-phosphate dehydrogenase 1-like (GPD1L) drive aberrant lipid droplet accumulation, which subsequently elevates FSP1 expression, enhances resistance to ferroptosis, and promotes peritoneal metastasis." (PMID 40862825, 2025). "Intriguingly, recent studies highlight GPD1L’s tumor-suppressive potential across diverse malignancies, including HER2-negative breast cancer, esophageal squamous cell carcinoma, and gastric carcinoma, though its role in CRC remained unexplored prior to this investigation." (PMID 40538846, 2025).
kidney cancer (2 papers, 2024 to 2026). Primary or metastatic malignant neoplasm involving the kidney. "These may include cancer types (e.g., ccRCC vs. non-ccRCC kidney cancer or bladder vs. kidney cancer), species (mouse vs. human), or experimental conditions (e.g., hypoxia, glycolysis, or dual knockdown of GPD1 and GPD1L)." (PMID 38689091, 2024).
metabolic syndrome (2 papers, 2015 to 2025). A cluster of metabolic risk factors for CARDIOVASCULAR DISEASES and TYPE 2 DIABETES MELLITUS. "The conserved tumor-suppressive activity across epithelial malignancies positions GPD1L as a promising therapeutic target for metabolic syndrome-associated cancers." (PMID 40538846, 2025).
sarcopenia (2 papers, 2022 to 2024). Progressive decline in muscle mass due to aging which results in decreased functional capacity of muscles. "A genome-wide association study on Korean cohorts showed that ribosomal protein S10 (RPS10), nudix hydrolase 3 (NUDT3), and glycerol-3-phosphate dehydrogenase 1 like (GPD1L) are genetic biomarkers of age-related sarcopenia." (PMID 39457696, 2024). "Combined with results of previous studies, the findings presented here suggest that GPD1L could be a genetic biomarker for sarcopenia, based on both miR-210 and HIF-1α pathways." (PMID 35241739, 2022). "Our study identified RPS10, NUDT3, and GPD1L as significant genetic biomarkers for sarcopenia." (PMID 35241739, 2022). "In addition, the loci near GPD1L were identified as significant biomarkers for ASM and SMI, which serve as novel index for sarcopenia." (PMID 35241739, 2022).
ventricular tachycardia (2 papers, 2018 to 2023). A disorder characterized by an electrocardiographic finding of three or more consecutive complexes of ventricular origin with a rate greater than a certain threshold (100 or 120 beats per minute are commonly used). "A loss-of-function GPD1L mutation (p.R189X; c.565C>T) was reported to cosegregate in a small family with ventricular tachycardia and sudden death." (PMID 38962240, 2023). "In conclusion, we report a novel rare GPD1L mutation (p.Arg189*) in a Chinese family with ventricular tachycardia, DCM, syncope and sudden death." (PMID 29077258, 2018).
adenoma (1 paper, 2024). A neoplasm arising from the epithelium. "Our results showed that, whether in the samples of cancer, adenoma or paracancer, the top three MP-RNA counted by partner numbers were coding for ASIC2, GPD1L and FAM213A, indicating that these three RNAs were always active in both normal and abnormal colon tissues." (PMID 38773399, 2024).
cardiac hypertrophy (1 paper, 2020). "Additionally, a long non-coding RNA related to cardiac hypertrophy, Chaer1, and genes related to hereditary arrhythmic disorders, including Ank2, Gpd1l, and Cacna2d1, were downregulated in the Rbm20S637A/S637A mice." (PMID 33110103, 2020).
cardiac ischemia (1 paper, 2016). "Our findings provided an additional layer of lincRNA-associated ceRNA regulation for GPD1L to influence metabolic state and electrophysiological activity of cardiomyocytes, which may lead to cardiac ischemia and heart failure." (PMID 28040802, 2016).
cholangiocarcinoma (1 paper, 2023). A carcinoma that arises from the intrahepatic biliary tree (intrahepatic cholangiocarcinoma) or from the junction, or adjacent to the junction, of the right and left hepatic ducts (hilar cholangiocarcinoma). "GPD1L exhibited downregulation in all tumour samples compared to adjacent normal tissue, except for hepato-biliary tumours (HCC and cholangiocarcinoma)." (PMID 37685919, 2023).
early repolarization syndrome (1 paper, 2021). "An additional variant in father (III:4) was present in the GPD1L gene, involved in the pathogenesis of early repolarization syndrome, Brugada syndrome type 2 and sudden cardiac death in children." (PMID 33829027, 2021). "The latest clinical study published in 2020 demonstrated that genetic alterations in the GPD1L gene led to decreased activation of the sodium channel and consequently early repolarization syndrome, one of the causes of sudden cardiac death." (PMID 33829027, 2021).
energy metabolism disorder (1 paper, 2025). "Taken together, we validated that downregulation of GPD1L could inhibit cell proliferation, increase cell apoptosis under oxidative stress, and lead to cell energy metabolism disorder." (PMID 40108995, 2025).